MTOR (mechanistic target of rapamycin kinase)
Diseases named in the same sentence as MTOR in open-access papers (continued):
Sharing a sentence is not in itself a finding about the gene and the disease.
breast tumor (continued). "Recently, gpNMB was found to augment WNT-1-mediated breast tumor initiation and growth by enhancing PI3K/AKT/mTOR pathway signaling and B catenin activity." (PMID 34016993, 2021). "In the present study, LNT treatment inhibited the growth of breast tumor along with a declined VEGF and HIF-1α levels, and the decreased AKT and mTOR activities." (PMID 33245358, 2020). "Our phosphoproteomic experiments established that exposure of breast tumor cells to SB-699551 curtails Gαi/o signaling and that of the PI3K/AKT/mTOR pathway, lending further evidence of its on-target activity." (PMID 32758183, 2020). "The PI3K/AKT/mTOR and RAS/MAPK/ERK pathways are related to the resistance to endocrine treatments in breast tumors and the PI3K/AKT/mTOR pathway always activated in HER2+ tumors." (PMID 33316872, 2020). "Parallel studies on CCL5 demonstrated its ability to induce small increases in breast tumor cell proliferation; in one of the research systems, such CCL5 activity was mediated by CCR5-dependent mTOR activation." (PMID 32582148, 2020). "We determined the activation of mTOR and its downstream substrates p70S6K and 4E-BP1, in breast tumor cells after transfection with SALL1." (PMID 29625565, 2018). "Our studies clearly showed that SALL1 expression in breast tumor cells selectively modulated the MAPK p38 and ERK1/2, as well as mTOR signaling pathways in tumor cells." (PMID 29625565, 2018). "In breast tumours, mTORC1 also controls angiogenic pathways via VEGF10, therefore, mTOR represents a validated target for the treatment of cancer." (PMID 28615679, 2017). "In two such breast tumours, we successfully inhibited tumour growth using a combination of PI3K and MTOR inhibitors." (PMID 28348404, 2017). "This particular breast tumour represents a case in which PLD1 and phospho-Akt are inversely expressed, and the PLD1/mTOR/p70S6k pathway is active in the cancer cells." (PMID 17726467, 2007). "The phosphatidylinositol 3-kinase (PI3K)/protein kinase B (AKT)/mammalian target of rapamycin (mTOR) signaling pathway (PAM pathway) plays a pivotal role in breast carcinogenesis, with approximately 70% of breast tumors exhibiting hyperactivation of this pathway." (PMID 40134916, 2025). "Additionally, HER2 initiates downstream signaling in the PI3K/Akt/mTOR and MAPK pathways, which are frequently dysregulated in breast tumors." (PMID 37662839, 2023). "This study demonstrates that different resistance drivers to PI3Kβi and AKTi converge to reactivate PI3K-AKT or mTOR signalling and combined inhibition of Mcl-1 and PI3K-AKT has potential as a treatment strategy for PI3Kβi/AKTi sensitive and resistant breast tumours." (PMID 36241868, 2022). "Our phosphoproteomic experiments established that exposure of breast tumor cells to SB-699551 elicited signaling changes in the canonical Gαi/o-coupled pathway and the phosphoinositide 3-kinase (PI3K)/AKT/mammalian target of rapamycin (mTOR) axis." (PMID 32758183, 2020). "In our data, p-mTOR, but not p-AKT or p-p70S6K, in breast tumors was associated with body fatness, despite that one would expect these markers to yield similar results and they were modestly correlated." (PMID 33024820, 2020). "In ERα-negative cells, adiponectin phosphorylated AMPK and blocked mTOR activation, thus inhibiting breast tumor growth." (PMID 31052147, 2019). "Our study suggests that the early identification of patients with a high ERα ENR of breast tumor cells, who may be resistant to ET, could lead to the inclusion of a CDK4/6 inhibitor or mTOR inhibitor in the treatment regimen." (PMID 31013810, 2019). "The percentages of positive expression for p-ER, EGFR, p-ERK1/2, p-mTOR and IGF1R were also in line with previous published data, using similar population selection, IHC methods, and assessment criteria in primary invasive breast tumors." (PMID 29486734, 2018).
breast tumor (continued). "Transfection of SALL1 but not mutated SALL1 in both MCF-7 and E0771 breast tumor cells significantly induced the phosphorylation of mTOR, p70S6K, and 4E-BP1, further confirming the activation of mTOR signaling in tumor cells after SALL1 expression." (PMID 29625565, 2018). "We performed phosphoproteomic analysis of MDA361, a HER2+/PIK3CAmut breast tumor line, treated without or with a highly selective mTOR-KI WYE-125132 (WYE-132)." (PMID 27015560, 2016). "In HER2+/PIK3CAmut breast tumor cells, an elevated mTORC2-ACL activity is prevalent and correlates with higher basal levels of acetyl-CoA and de novo lipid synthesis, both of which were more substantially inhibited by mTOR-KI than rapamycin." (PMID 27015560, 2016). "Alterations in estrogen signaling pathways in ERα+ breast tumors can arise from increased growth factor signaling, such as epidermal growth factor receptor (EGFR) and AKT/mammalian target of rapamycin (mTOR) pathways, and more recently to ERα isoform variation." (PMID 29657266, 2016). "We hypothesized that women who had “sufficient” recreational PA levels would have lower mTOR pathway activity in breast tumors compared with women who had “insufficient” or no PA." (PMID 36895729, 2023). "Finally, eIF4E might confer tamoxifen resistance via oestrogen receptor independent pathway due to the activity of mTOR and MNK1, one of the downstream modulators being RUNX2 which is found to be important in breast tumour growth and metastasis." (PMID 32066877, 2020). "Therefore, our results suggest that high activity of the PI3K/AKT/mTOR pathway in breast tumors would induce degradation of FOXO3 protein, but not FOXO1 protein." (PMID 32332845, 2020). "Perhaps integrin‐β1 blockade facilitates chemotherapeutic eradication of breast tumor cells with metastasis‐initiating capacity, whereas PI3K/mTOR inhibition does not." (PMID 34058066, 2022).
liver fibrosis (117 papers, 2011 to 2026). "Improvements in choline-phosphatidylcholine metabolism and inhibition of PI3K/AKT/mTOR signaling appeared to be the underlying mechanism that restored cell membrane, attenuated stellate cell activation and suppressed the progression of liver fibrosis." (PMID 36698192, 2023). "Exosomes originated from human adipose mesenchymal stem cells (hADMSCs-Exo) were shown to inhibit HSCs activation and rectify choline metabolism disorders via PI3K/Akt/mTOR pathway to ameliorate liver fibrosis, especially caused by NAFLD." (PMID 37539053, 2023). "In conclusion, this study demonstrated that mitophagy regulated by the mTOR signaling pathway plays a dual protective role in liver fibrosis associated with selenium." (PMID 35745140, 2022). "On the contrary, mounting evidence suggests that increased autophagy levels via inhibition of mTOR signaling pathway have been associated with reduction of HSCs activation and alleviation of liver fibrosis." (PMID 35185602, 2021). "It has been shown that dysregulated mTOR signaling is closely associated with pulmonary fibrosis, liver fibrosis and SSc." (PMID 32708044, 2020). "Growing evidence has implicated aberrant mTOR activation in liver fibrosis and pathogenesis." (PMID 37131258, 2023). "Firstly, the key regulatory proteins involved in the mTOR signaling pathway were few, and subsequent studies can focus on more proteins to comprehensively investigate the role of the mTOR signaling pathway in regulating mitophagy in the association between selenium and liver fibrosis." (PMID 35745140, 2022). "Therefore, the aim of the present study was to investigate the function of mTOR overactivation in mesenchymal cells in CCl4− induced liver fibrosis and to reveal possible mechanisms underlying its participation in fibrotic diseases." (PMID 27819329, 2016). "In addition to the PI3K/Akt/mTOR signaling pathway, the NF-κB pathway might also be involved in the underlying mechanism of TA against liver fibrosis." (PMID 35359829, 2022). "Current evidence underscores the significance of PI3K/AKT/mTOR-regulated autophagy in the reversal of liver fibrosis." (PMID 41601875, 2026). "The PI3K/Akt/mTOR signaling pathway participates in the process of liver fibrosis by regulating the proliferation and apoptosis of HSCs and the synthesis and degradation of ECM." (PMID 39388703, 2025). "In conclusion, Huangqi Decoction enhances autophagy and inhibits apoptosis through the PI3K/Akt/mTOR pathway in rats with liver fibrosis." (PMID 39388703, 2025). "Further research is warranted to delineate the specific mechanisms by which Qijia Rougan decoction inhibits HSC activation and autophagy in the context of liver fibrosis via the PI3K/AKT/mTOR pathway." (PMID 40391189, 2025). "Since a high expression of mTOR worsens CCl4-induced fibrosis, mTOR is considered one of TGF-β’s partners in inducing liver fibrosis." (PMID 39968080, 2025). "The PI3K/AKT/mTOR signaling pathway promotes liver fibrosis progression through cellular growth regulation, differentiation, and programmed cell death and promoting epithelial-mesenchymal transition (EMT)." (PMID 40243656, 2025). "During the infection with the hepatitis B virus (HBV), the activation of the PI3K/Akt/mTOR signaling pathway is capable of elevating the viral load and the extent of liver fibrosis." (PMID 40005877, 2025). "In conclusion, our study indicates that Huangqi Decoction exerts a hepatoprotective effect against CCL4-induced injury, promotes autophagy, and suppresses apoptosis through the PI3K/Akt/mTOR signaling pathway in hepatic fibrosis rats." (PMID 39388703, 2025). "These bioactive compounds operate through various pathways, including the TGF-β/Smad signaling pathways, AMPK/mTOR, Wnt/β-catenin, NF-κB, PI3K/AKT/mTOR, hedgehog pathways, and other factors associated with hepatic fibrosis." (PMID 39273295, 2024).
liver fibrosis (continued). "Next, in order to verify that BMSCs eased liver fibrosis through PI3K/AKT/mTOR pathway, we detected its expression in vivo." (PMID 38736295, 2024). "The upregulated expression of miR23a-5p activates the PI3K/AKT/mTOR/Snail pathway to activate hepatic stellate cells and induce hepatic fibrosis, providing new therapeutic targets for the treatment of liver fibrosis." (PMID 39595622, 2024). "In the experimental model of hepatic fibrosis, following hepatic cell injury, activation of the mTOR pathway in mesenchymal cells enhanced the wound healing response." (PMID 39698464, 2024). "Here, we demonstrate the downregulation of KIF18A in HSCs and liver fibrosis tissues, and identify its role in HSC activation and hepatic fibrosis induction through Akt/mTOR-signaling pathway." (PMID 38372748, 2024). "TDF directly ameliorates liver fibrosis by downregulating the PI3K/Akt/mTOR signaling pathway, which results in the apoptosis of activated HSCs." (PMID 39359922, 2024). "The downregulation of KIF18A subsequently results in elevated p-AKT levels, ultimately activating the AKT/mTOR-signaling pathway and promoting the initiation and progression of liver fibrosis." (PMID 38372748, 2024). "Doxazosin inhibits autophagy by activating the PI3K/Akt/mTOR signaling pathway, attenuating liver fibrosis." (PMID 39175576, 2024). "Overexpression of the ACE2 protein activates the AMPK/mTOR pathway, modulates HSCs autophagy, suppresses HSCs activation, and decelerates the progression of liver fibrosis in individuals with NAFLD." (PMID 39175576, 2024). "Doxazosin has been observed to inhibit autophagy by stimulating the PI3K/Akt/mTOR pathway, attenuating liver fibrosis." (PMID 39175576, 2024). "Novel studies have revealed that Tregs are relevant in the development of liver fibrosis, and it has been shown that signaling via the mammalian target of rapamycin (mTOR) is involved in orchestrating the protective function of Tregs." (PMID 39063116, 2024). "In summary, overactivation of mTOR within the mesenchymal compartment exacerbated liver fibrosis induced by CCl4." (PMID 39698464, 2024). "The omics analysis revealed that the key mechanism of hADMSCs-Exo anti-hepatic fibrosis was the inhibition of PI3K/AKT/mTOR signaling pathway and affecting the changes of metabolites in lipid metabolism, and mainly regulating choline metabolism." (PMID 36698192, 2023). "Overall, the findings indicated that anti-PCSK9 treatment improved liver fibrosis by regulating hypoxia-induced autophagy in hepatocytes through the AMPK/mTOR/ULK1 signaling pathway." (PMID 37466835, 2023). "Dietary polyphenols have anti-inflammatory and antioxidant properties, and they have been reported to inhibit TGF-β/Smad, Wnt/β-catenin, NF-κB, PI3K/AKT/mTOR, hedgehog pathway, or activate the AMPK/mTOR pathway to reverse liver fibrosis." (PMID 38202710, 2023). "Phosphatidylinositol 3 Kinase PI3K/AKT/mTOR-mediated autophagy was demonstrated to play a role in reversing liver fibrosis." (PMID 37108648, 2023). "Anti-PCSK9 treatment alleviates liver fibrosis by regulating hypoxia-induced autophagy in the hepatocytes through AMPK/mTOR/ULK1 signaling pathway." (PMID 37466835, 2023). "Sung Won Lee found that TDF directly ameliorates liver fibrosis by downregulating the PI3K/Akt/mTOR signaling pathway, which leads to apoptosis of activated HSC." (PMID 36915044, 2023). "In a mouse model of liver fibrosis, TDF leads to aHSC apoptosis by downregulating the PI3K/Akt/mammalian target of rapamycin (mTOR) signaling pathway and ultimately improving liver fibrosis." (PMID 37298621, 2023). "Baicalin helps to increase the number of bacteria producing SCFA, reduces the phosphorylation of PI3K, AKT and mTOR, and lowers the level of IL-17 to inhibit liver fibrosis." (PMID 38202710, 2023). "At present, studies on the mechanism of mitophagy regulated by the mTOR signaling pathway in liver fibrosis are limited." (PMID 35745140, 2022).
liver fibrosis (continued). "We demonstrated that tenofovir disoproxil fumarate, an antiviral drug for HBV, directly ameliorates liver fibrosis in mice by downregulating the PI3K/Akt/mTOR signaling pathway, which results in the apoptosis of activated hepatic stellate cells." (PMID 35052861, 2022). "The present study provided evidence that mitophagy regulated by the mTOR signaling pathway plays a dual protective role on low-selenium inducing liver fibrosis and nano-selenium supplements preventing liver fibrosis." (PMID 35745140, 2022). "Other studies have reported that salvianolic acid A inhibits liver function, hepatic fibrosis index, and collagen deposition by inhibiting the PI3K/AKT/mTOR signal cascade and alleviates the hepatic fibrosis by improving hepatic fibrosis degree." (PMID 36277879, 2022). "Studies have shown that autophagy is dependent on ROS, mTOR, and IL-7, and another factor in the process of liver fibrosis." (PMID 35529927, 2022). "In the current study, we discovered that the activation of Rheb/mTOR pathway drives the tendency to liver fibrosis, which is consistent with findings in other liver diseases." (PMID 33295107, 2021). "Energy deprivation along with stressful stimuli in qHSCs inhibit mTOR signaling pathway, which is the main endogenous regulator of the autophagy during liver fibrosis." (PMID 35185602, 2021). "This evidence imply that lncRNAs can reduce the activation response of HSC by inhibiting the activation of PI3K/AKT/mTOR signaling pathway in liver fibrosis." (PMID 34899344, 2021). "As previous studies, mTOR signal pathway inhibition suppressed liver fibrosis in other liver disease models." (PMID 33295107, 2021). "TDF directly ameliorates liver fibrosis by downregulating the PI3K/Akt/mTOR signalling pathway, which results in the apoptosis of activated HSCs." (PMID 34879114, 2021). "In vitro studies have shown that naringin decreases hepatic stellate cell activity and inhibits liver fibrosis by inhibiting mTOR-autophagy." (PMID 33953669, 2021). "In conclusion, our data prove that RvD1 inhibits HSCs autophagy by regulating AKT/mTOR signaling pathway, which reduces HSCs activation and blocks the occurrence and development of liver fibrosis." (PMID 34987404, 2021). "Previously, LUTN prevents the progression of liver fibrosis induced by carbon tetrachloride-(CCL4) through targeting AKT/mTOR/p70S6K and TGFβ/Smad signaling pathways." (PMID 34439516, 2021). "In conclusion, this study demonstrated that TDF directly ameliorates liver fibrosis through the downregulation of the PI3K/Akt/mTOR signalling pathway, which results in the apoptosis of activated HSCs." (PMID 34879114, 2021). "Abolitions of HI activation were noted for mTOR signaling, hepatic fibrosis signaling, and ILK signaling." (PMID 33923910, 2021). "Autophagic degradation of Cav-1 and F-actin remodeling were increased in CCL4-induced LSEC defenestration and liver fibrosis by inhibiting the NO-dependent PI3K-Akt-mTOR pathway." (PMID 32724454, 2020). "It has been proposed as a healthcare product against hepatic fibrosis with remarkable ability to inhibit the expression of p-mTOR/mTOR level and sequentially promote autophagy." (PMID 32265720, 2020). "miR-23a interacts with and degrades PTEN to further influence the downstream pathway PI3K/AKT/mTOR/Snail in hepatic fibrosis." (PMID 33085646, 2020). "Intriguingly, lncRNA GAS5 acts as a sponge platform to competitively decrease miR-23a expression, and miR-23a degrading PTEN further influenced the downstream pathway PI3K/Akt/mTOR/Snail in hepatic fibrosis." (PMID 33240872, 2020). "These UDCA-induced effects were completely abolished by an autophagy inducer, rapamycin, suggesting a crucial role of Akt/mTOR-mediated autophagy inhibition in the progression of liver fibrosis." (PMID 32724454, 2020). "The overactivation of mTOR in mesenchymal cells by conditional deletion of TSC1 exacerbated CCl4-induced liver fibrosis, which was reversed by mTOR inhibitor rapamycin." (PMID 32708044, 2020).